APLN (apelin)
Diseases named in the same sentence as APLN in open-access papers (continued):
Sharing a sentence is not in itself a finding about the gene and the disease.
Cerebral ischemia (9 papers, 2015 to 2023). Restriction of arterial blood supply to the brain associated with insufficient oxygenation to support the metabolic requirements of the tissue. "Apelin-13 is a neuropeptide which is capable of protecting against neuronal apoptosis and excitotoxicity in vitro, and is associated with neuronal survival in vivo following cerebral ischemia or ischemia/reperfusion injury, amyotrophic lateral sclerosis (ALS), and seizure." (PMID 33171641, 2020). "Following cerebral ischemia, apelin-13 promotes angiogenesis, increases the stability of atherosclerotic plaques and reduces excitatory toxicity, thereby improving prognosis." (PMID 36034795, 2022). "In this review, we have discussed the role of apelin-13 in the regulation of cerebral ischemia and the underlying mechanisms, along with the therapeutic potential of the apelin-13/APJ signaling pathway in cerebral ischemia." (PMID 36034795, 2022). "Apelin-13 is one of the subtypes of apelin, and the apelin-13/APJ signaling pathway protects against cerebral ischemia by promoting angiogenesis, inhibiting excitotoxicity and stabilizing atherosclerotic plaques." (PMID 36034795, 2022). "To this end, we first need to clarify the biological functions and mechanism of apelin-13/APJ signaling in cerebral ischemia, and the long-term effects of activating this pathway." (PMID 36034795, 2022). "In this review, we have summarized the role and mechanism of apelin-13 in cerebral ischemia, in order to offer new insights into its diagnosis and treatment." (PMID 36034795, 2022). "HUK-enhanced expression of VEGF and apelin/APJ in ERK1/2 dependent waymay serve as an alternative mechanism for inducing angiogenesis after cerebral ischemia." (PMID 26222055, 2015). "In terms of pathological conditions, Apelin-13 injection into the tail vein of male rats with cerebral ischemia was found to prevent NO depletion, thereby reducing neuronal death and the cerebral infarct volume and significantly improving sensorimotor balance defects." (PMID 38089606, 2023). "Similarly, the injection of Apelin-13 into the right ventricle significantly increases Bcl-2/Bax to alleviate neuronal apoptosis in mice with cerebral ischemia/reperfusion." (PMID 38089606, 2023). "Clinical studies suggest that apelin is related to the diagnosis and prognosis of cerebral ischemia, while studies in animal and cellular models indicate that exogenous apelin-13 can effectively reduce infarct volume and cerebral edema, and improve neurological function after cerebral ischemia." (PMID 36034795, 2022). "Likewise, previous study manifests that apelin-13 exerts a protective role for neurons against cerebral ischemia/reperfusion (I/R) injury through inhibiting the expression of inflammatory factors (IL-1β, TNF-α, and ICAM-I) and the activation of microglia and astrocytes." (PMID 31040784, 2019). "Studies increasingly show that the apelin/apelin receptor (APJ) signaling pathway is involved in the occurrence and development of cerebral ischemia." (PMID 36034795, 2022). "Recent study showed Apelin 13 induced AMPK phosphorylation and protected cell apoptosis in cerebral ischemia insults." (PMID 30709405, 2019). "In addition, the variation loci related to the apelin/APJ system, their relationship with brain structure and function, and their impact on the prognosis of cerebral ischemia also need to be elucidated." (PMID 36034795, 2022). "Apelin-13 could stimulate AMPK activity in myocardial microvascular endothelial cells; it up-regulated AMPK phosphorylation levels in cerebral ischemia insults, and AMPK signals were involved in the mechanism of apelin-13-mediated neuroprotection." (PMID 33171641, 2020).
depression (9 papers, 2018 to 2025). "Second, we sought to elucidate the association between the total serum and plasma apelin levels and the severity of depressive symptoms using the Montgomery–Åsberg Depression Rating Scale (MADRS), a standardized measure of depressive symptomatology." (PMID 39769424, 2024). "This positive correlation between reduced apelin levels and more severe depressive symptoms may initially seem counterintuitive, as many studies have suggested that lower apelin levels are associated with depression." (PMID 39769424, 2024). "In conclusion, the findings of this study clearly indicate that hot water extracts from pine needles (PN) activate the Apelin signaling pathway, alleviating neuroinflammation and promoting neurogenesis in models of depression." (PMID 41268325, 2025). "This is the first report on PN regulating the apelin signaling pathway in a depression-like mouse model, which in turn alleviates neuroinflammation, enhances BDNF production, and improves the production of neurotransmitters." (PMID 41268325, 2025). "Apelin alleviates the onset of depression through its function in promoting BDNF production, anti-inflammatory, and anti-oxidative mechanisms." (PMID 41268325, 2025). "GSVA analysis revealed that the gene profiles of AD patients with depression were mainly enriched in the T-cell receptor signaling pathway, GnRH signaling pathway, Apelin signaling pathway, and the cGMP-PKG signaling pathway, etc." (PMID 41333466, 2025). "Depression has a complex origin, and the Apelin/APJ system is currently understood to engage in crosstalk through neuroendocrinology, neurotrophic factors, and inflammation." (PMID 41268325, 2025). "The neuroprotective potential of apelin is further enhanced by its anti-inflammatory and antioxidant activity, essentially counteracting some of the common mechanisms of depression." (PMID 41375608, 2025). "This is further supported by studies indicating that apelin-13 administration induces a depression-like phenotype in mice, and that lower levels of apelin are found in individuals with anorexia nervosa." (PMID 39769424, 2024). "Future studies should consider these factors and explore the role of apelin in different depression subtypes and its interactions with other biomarkers to provide a more comprehensive understanding of its clinical potential." (PMID 39769424, 2024). "Specifically, the intracerebroventricular (ICV) administration of apelin-13 in rats was shown to reverse depression-like behaviors induced by chronic stress models, including social defeat and unpredictable chronic mild stress (UCMS)." (PMID 39769424, 2024). "Chronic i.c.v. infusion of 2 μg apelin-13 upregulated the brain-derived neurotrophic factor (BDNF) against chronic stress-induced depression-like phenotypes by ameliorating HPA axis and hippocampal glucocorticoid receptor dysfunctions." (PMID 32231577, 2020). "In a rat model of depression, apelin-13 treatment elicits antidepressant effect and improves recognition memory via activating phosphatidylinositol 3-kinases (PI3K) and extracellular signal-regulated kinase 1/2 (ERK1/2) signaling pathways." (PMID 31718027, 2019). "Thus, not only does apelin reduce neuroinflammation in depression, but it also protects the CNS from oxidative stress." (PMID 41375608, 2025). "Specifically, this positive correlation could indicate that in cases of more severe depression, apelin might be involved in a compensatory or adaptive mechanism aimed at mitigating certain symptoms." (PMID 39769424, 2024). "These contrasting findings highlight the complexity of the role of apelin in depression and underscore the need for further research to clarify how plasma and serum apelin levels influence depressive states differently, and to determine which is a more accurate biomarker for mood disorders." (PMID 39769424, 2024).
depression (continued). "However, our study’s findings suggest that lower plasma apelin levels are associated with greater depression severity, indicating a potential inverse relationship between apelin levels and depression in our sample." (PMID 39769424, 2024). "Our study contributes to the growing body of literature on the role of apelin in depression." (PMID 39769424, 2024). "Similarly, in another clinical study, serum apelin levels were found to be significantly higher in patients diagnosed with depression compared to healthy controls." (PMID 39769424, 2024). "The different effects of apelin on depression, however, may be due to different injection methods and/or different animal species." (PMID 32231577, 2020). "The role of apelin in depression, however, is controversial." (PMID 32231577, 2020). "Similarly, intracerebral infusion of apelin-13 can ameliorate depression-like phenotypes in rats subjected to chronic restraint stress." (PMID 31718027, 2019). "In order to determine whether Xiaoyaosan regulated the apelin-APJ system in the mouse model of depression, the expressions of apelin and APJ were measured." (PMID 29751542, 2018). "The apelin/APJ system is strongly expressed in the brain, and plays a bi-directional regulatory role in pain, depression, and memory." (PMID 32231577, 2020). "Therefore, this study established a mice depression model by three weeks of CUMS, and observed the effect of Xiaoyaosan intervention on the depressive-like behaviors and the changes of the apelin-system in the hypothalamus." (PMID 29751542, 2018). "However, the metabolic effects of apelin (increasing insulin sensitivity, glucose uptake, thermogenesis, and normalising lipid profile) are without a doubt beneficial in depression’s pathophysiology." (PMID 41375608, 2025).
Hyponatremia (9 papers, 2017 to 2024). An abnormally decreased sodium concentration in the blood. "In short-term severe hypothyroidism, serum apelin level is markedly decreased, which may predispose susceptible patients to hyponatremia, while the level of copeptin is unchanged." (PMID 36187132, 2022). "In patients with the syndrome of inappropriate antidiuresis, in which vasopressin hypersecretion leads to hyponatremia, the balance between apelin and vasopressin is significantly altered." (PMID 34880830, 2021). "Apelin, regulating angiogenesis and stimulating endothelial cell proliferation and migration, was proved to be a useful biomarker for cancer disease progression evaluation beyond kidney failure and hyponatremia." (PMID 36830782, 2023). "Furthermore, apelin and vasopressin secretion are significantly altered in various water metabolism disorders including hyponatremia and polyuria-polydipsia syndrome." (PMID 28620355, 2017). "Previous studies showed that systemic apelin and AVP secretion are significantly altered in various water metabolism disorders, including hyponatremia and polyuria-polydipsia syndrome." (PMID 33868005, 2021). "Here, the authors report that a metabolically stable apelin-17 analog, by acting at the kidney level, reduces AVP-induced antidiuresis and improves hyponatremia in rodents, demonstrating a potential approach for treating water metabolism disorders." (PMID 33436646, 2021). "The administration of LIT01-196 (900 nmol/kg, s.c.) for two days in this rat model of hyponatremia, by re-establishing the “AVP/(apelin + LIT01-196)” balance, inhibited the effects of AVP on urine output and urine osmolality effectively, and induced a progressive correction of plasma sodium levels." (PMID 34880830, 2021). "Following these findings, a recent study investigated whether empagliflozin improves hyponatremia through affecting apelin and AVP, two neuropeptides which regulate water homeostasis in opposing ways; AVP by promoting antidiuresis, whereas apelin by augmenting diuresis." (PMID 39435353, 2024). "The plasma apelin to copeptin ratio was lower in CHF patients than in controls, suggesting that the mild increase in apelin secretion could not counteract the major increase in AVP secretion, leading to abnormal water metabolism and hyponatremia." (PMID 28620355, 2017).
non-alcoholic fatty liver disease (9 papers, 2011 to 2025). "Non-alcoholic fatty liver disease (NAFLD) patients’ samples revealed a correlation between serum apelin and NAFLD activity score." (PMID 37670786, 2023). "The present study aimed to investigate the expression of apelin in nonalcoholic fatty liver disease (NAFLD) and the mechanism of apelin promoting hepatic fibrosis through ERK signaling in hepatic stellate LX-2 cells." (PMID 31270645, 2019).
Sepsis (9 papers, 2018 to 2025). Sepsis is defined as life-threatening organ dysfunction caused by a dysregulated host response to infection. "For example, in human sepsis, endogenous apelinergic levels rise early, and specific enzymatic breakdown activities potentially threaten endogenous apelin system reactivity and negatively impact the outcome." (PMID 37510916, 2023). "Endogenous apelinergic levels early rose, and specific enzymatic breakdown activities potentially threatened endogenous apelin system reactivity and negatively impacted the outcome in human sepsis." (PMID 34815457, 2021). "This will pave the way to implement optimization strategies for advancing the apelin system as a target of therapeutic intervention in sepsis." (PMID 34815457, 2021). "Principal component analysis (PCA) was performed on 15 intercorrelated continuous variables related to sepsis outcomes and apelin system metabolism, revealing two principal subspaces (PC1 and PC2) accounting for 19.46 and 23.94%, respectively." (PMID 34815457, 2021). "Apelin, a multifunctional cytokine, has a variety of physiological functions and pathophysiological effects in mammals, including regulating immune responses to improve outcomes in sepsis." (PMID 38359069, 2024). "From this standpoint, apelin system disturbance could influence the severity of sepsis and septic shock, opening doors for future explorative studies." (PMID 34815457, 2021). "Whether the observed responsiveness of the apelin system in human sepsis and septic shock is appropriate is, however, unclear." (PMID 34815457, 2021). "This study is the first reporting a positive hemodynamic impact of APLN-13 infusion in a large animal model of septic shock and revealing simultaneous intricate homeostatic disturbances among the renin-angiotensin, kallikrein-kinin, and apelin systems involved in outcomes of acute human sepsis." (PMID 34815457, 2021). "Apelin is a peptide hormone with anti-oxidative and anti-inflammatory activities and is proposed to be a potential therapeutic for many disease conditions, including sepsis." (PMID 30061611, 2018). "Serum apelin-13 could protect against sepsis-induced ALI by regulating NOX4-dependent ROS." (PMID 36959535, 2023). "Furthermore, the short-term exogenous apelin-13 infusion helps stabilize cardiorenal functions in ovine septic shock; however, this ability might be impaired by specific enzymatic systems triggered during the early course of human sepsis." (PMID 37510916, 2023). "report that apelin suppresses the inflammatory response and promotes cell survival partially via activating the PI3K and AKT pathways in a mouse model of postburn sepsis." (PMID 30061611, 2018). "Apelin-13 downregulates the production of NADPH oxidase 4 and ROS through the APJ receptor, inhibits macrophage glycolysis, and reduces pulmonary inflammation in mice with sepsis." (PMID 37629199, 2023). "In sepsis, knowledge is lacking on how this apelin system is reactive; if it has therapeutic potential in larger animal models, and what is potentially affecting the homeostasis of the apelinergics in this context." (PMID 34815457, 2021).
brain tumor (8 papers, 2014 to 2024). "We have gained important insight into APLN/APLNR-mediated effects in brain tumor associated neurons, astrocytes, the vasculature (consisting of ECs and pericytes), as well as the immune compartment (formed by tumor-associated myeloid cells and T-lymphocytes)." (PMID 34359800, 2021). "Here we summarize the current evidence on the role of APLN/APLNR signaling during brain tumor pathology." (PMID 34359800, 2021). "In particular, APLN has been shown to be needed for intersomitic vessel angiogenesis and the promotion of angiogenesis in brain tumors." (PMID 25481245, 2014). "APLN expression has been observed to be highly up-regulated in the microvasculature in brain tumors." (PMID 25481245, 2014). "These brain tumour models could also act as ideal platforms for the screening of potential drugs targeting the apelin signalling axis." (PMID 38803685, 2024). "Expression and role of apelin/APJ signaling in brain tumor and HCC." (PMID 33912466, 2021). "Consequently, survival of GBM-bearing mice was significantly increased when APLN expression was missing in the brain tumor microenvironment." (PMID 32545380, 2020). "Aplnr and apelin appear to be co-localized in endothelial cells in and around microvascular proliferations in brain tumour specimens and we speculate that most aplnr and apelin co-expression in the kidney is likely to be in vascular elements." (PMID 28817612, 2017). "All these results revealed that apelin/APJ axis may play an important role in brain tumor." (PMID 33912466, 2021). "However, the relationship between APLN/APLNR and prognosis of brain tumor is still unknown." (PMID 36193059, 2022).
diabetic retinopathy (8 papers, 2011 to 2025). "Apelin, a regulator of insulin sensitivity, has demonstrated protective effects in diabetic retinopathy, while galectin-3 has been identified as a key factor in fibrosis and inflammatory responses, particularly in nephropathy and neuropathy." (PMID 40137149, 2025). "The apelin/APJ system is involved in vascular function and may exert protective effects in diabetic retinopathy by preventing pericyte loss and vascular leakage." (PMID 40137149, 2025). "Moreover, apelin’s involvement in promoting diabetic retinopathy underscores the need for caution to prevent complications in other organs." (PMID 39857634, 2024). "Recent studies have suggested that apelin contributes to the pathogenesis of diabetic retinopathy." (PMID 23874984, 2013). "Numerous studies have investigated the role of apelin, one of the APJ ligands, in the development of diabetic retinopathy." (PMID 39802191, 2025). "Additionally, apelin-13 might play a role in retinal neovascularization under diabetic retinopathy." (PMID 29875677, 2018). "In diabetes-related diseases, such as diabetic retinopathy or nephropathy, the apelin-13 level was significantly elevated in comparison to non-diabetic organs." (PMID 29875677, 2018).